INS (insulin)
Diseases named in the same sentence as INS in open-access papers (continued):
Sharing a sentence is not in itself a finding about the gene and the disease.
Hyperglycemia (continued). "The symptoms of chronic intraperitoneally GnIH-treated piglets exhibited hyperglycemia, a glucose intolerance, hypoinsulinism and hyperglucagon, which prompted us to decipher the molecular mechanism underlying the GnIH-mediated insulin resistance in insulin-stimulated glucose disposal tissues." (PMID 36430435, 2022). "SCN lesions in rats have been shown to abolish the daily rhythms in plasma concentrations of glucose and insulin, and genetic disruption of clock genes in mice, such as in Clock and Bmal1 mutant mice, cause hyperglycemia, hypoinsulinemia, and altered adipogenesis and hepatic carbohydrate metabolism." (PMID 36160856, 2022). "Furthermore, attenuation of autophagy in beta cells of pancreas was recorded during aging and was assumed to induce age-related diabetic changes such as decreased insulin secretion, decreased beta cell mass and function, and hyperglycemia; well-known risk factors for ischemic heart disease." (PMID 35416562, 2022). "Hence, insulin insensitivity results in increased intestinal glucose absorption, increased renal glucose reabsorption, and impaired peripheral tissue glucose uptake causing hyperglycemia." (PMID 36060656, 2022). "Moreover, insulin resistance of liver cells plays an important role in the pathogenesis of the disease, which is associated with increased lipid synthesis in the liver, thus leading to the development of hypertriglyceridemia and hyperglycemia." (PMID 35600209, 2022). "Furthermore, intensive insulin therapy has been shown to reduce mortality by 34%, and bloodstream infections by 46% during hospitalization, and those with hyperglycemia who received insulin infusion showed a lower risk of severe disease than those who did not receive insulin infusion." (PMID 35530861, 2022). "Risk factors for hyperglycemia in premature newborns include excessive parenteral glucose infusion rates in addiction to endogenous rates of glucose production (4–7 mg/kg/min), low-insulin-dependent tissues (fat and muscle), and a limited insulin response to glucose." (PMID 36290668, 2022). "Similarly, skipping breakfast may also trigger hyperglycemia and high glycated hemoglobin after lunch and dinner, further leading to impaired insulin response and thus increasing the risk of T2D." (PMID 35399945, 2022). "Moreover, the lower number of hypoglycemic episodes associated with reduced insulin therapy (both subcutaneous and intravenous) resulting from minor stress admission hyperglycemia further corroborated the reduced in-hospital occurrence of arrhythmias in SGLT2-i users." (PMID 36237914, 2022). "Importantly, these impairments were associated with increased blood insulin levels, suggesting that the heparin‐induced hyperglycaemia and glucose intolerance may be due to impaired insulin action." (PMID 34277977, 2021). "The findings presented here illustrate that insulin therapy might seem as more appropriate than other anti-DM pharmacotherapies in the management of COVID-19 patients with DM due to low risk of uncontrolled hyperglycemia and diabetic ketoacidosis (DKA)." (PMID 34124187, 2021). "Since heparanase exerts properties to enhance insulin-induced proliferation in breast carcinoma cells in vitro, authors have reported a relevant association between lymph node metastases and the simultaneous existence of both hyperglycaemia and heparanase expression." (PMID 34070058, 2021). "However, insulin should be the first injectable if there is evidence of ongoing catabolism (weight loss), symptoms of hyperglycemia (i.e. polyuria, polydipsia), very high levels of glycemia (HbA1c >10% or fasting plasma glucose [FPG] ≥300 mg/dL), or if type 1 diabetes is likely." (PMID 34165382, 2021). "Additionally, the use of glucocorticoids was found to be associated with hyperglycemia resulting from the increase in glucose resistance, the reduction in insulin secretion, and the induction of β-cells apoptosis leading to reduced expression of glucose transporter 2 and glucokinase." (PMID 33810367, 2021).
Hyperglycemia (continued). "This depends on several mechanism such as insulin resistance, deficient proinsulin processing by pancreatic beta cells, abnormal glucagon response, and lack of suppression of hepatic glucose release following intravenous glucose infusion that have been suggested to contribute to hyperglycemia." (PMID 33796072, 2021). "Additionally, T1D is associated with a low bone mineral density (BMD) and an increased risk of fracture, resulting from ablation of the insulin bone-anabolic effect, the toxic hyperglycemia, inflammation, oxidative stress, and superfluous urinary calcium excretion." (PMID 33671138, 2021). "Patients using this system are still at risk for hypoglycemia because of insulin on board, exercise, overdosing on carbohydrates, and/or hyperglycemia, so a notification for predicted hypoglycemia using advanced machine learning models with good performance could still be clinically useful." (PMID 33913816, 2021). "Increasing sympathetic activity upon awakening from naps, mainly prolonged naps, could results in disruption of the sympathovagal balance, activation of the renin-angiotensin system, which can minimize pancreatic beta-cell insulin secretion, insulin resistance and associated hyperglycemia." (PMID 33921201, 2021). "Furthermore, bone loss in peri-implant tissues of these mice was remarkably higher than those in diabetic mice with normoglycemia or persistent hyperglycemia, suggesting that ineffective insulin signaling may aggravate the process of bone loss." (PMID 34401982, 2021). "Insulin is well known for its ability to potently stimulate glucose uptake and glycogen synthesis in skeletal muscles, and conditions that limit glycogen synthesis in this tissue are associated with hyperglycemia and other metabolic disorders typically found in T2D patients." (PMID 34580412, 2021). "However, prolonged hyperglycemia may cause irreversible damage to the function of pancreatic islet ß-cells, resulting in an absolute decrease in insulin secretion." (PMID 33381036, 2020). "However, the necessity of insulin treatment could function as a proxy for more cardiovascular burden and generally less successful management of hyperglycemia, subsequently leading to higher risk of dementia (reverse causality)." (PMID 32741836, 2020). "The possible reason might be ascribed to the pharmacological properties of the α2-adrenoceptor agonists itself, which can cause hyperglycemia by a mechanism that involves the postsynaptic α2-adrenoceptor stimulation of pancreatic beta cells, which inhibits insulin secretion." (PMID 32359367, 2020). "Interestingly, carriers of the minor allele (G), besides having a lower risk of hypertension as well as lower body weight, fasting-insulin, and hyperglycemia, appear to be more protected if following a Mediterranean diet and/or when their MUFA intake was >13.2% of total energy." (PMID 32466599, 2020). "Indeed, Ire1, which is one of the effector branches of the UPR, when continuously activated has been shown to cause suppression of insulin gene expression, possibly explaining why prolonged hyperglycemia in T2D patients leads to diminished insulin production also in the absence of apoptosis." (PMID 30837889, 2019). "Since such a use of insulin or exercise as a means to oppose hyperglycemia post-exercise may increase the risk of hypoglycemia if the insulin dose or the duration of the cool-down session is excessive these strategies should be adopted only if accompanied by regular blood glucose monitoring." (PMID 31258513, 2019). "Recent studies have hypothesized a critical role for the regular increases in insulin that occur throughout the day in association with meal-induced hyperglycemia and provided evidence for a powerful postprandial effect of insulin to conserve sodium after meals." (PMID 30862903, 2019).
Hyperglycemia (continued). "Thus, DNAm may influence biological mechanisms of tissue response to hyperglycemia different from those implicated by genetic studies, which appear to be primarily associated with β cell function and insulin activity." (PMID 32274260, 2019). "A normal cause variation could be defined as any hypoglycemia or hyperglycemia incidences with the underlying cause known to the patient herself or himself and also referred as predictable (patient controllable) factors such as insulin injection, diet intake, physical activity, and others." (PMID 31042157, 2019). "Considering that excessive ROS production is closely associated with an inflammatory response and impaired insulin signaling in extramedullary adipocytes, further dysfunctions in BMAds in the settings of hyperglycemia could be expected and are worth investigating." (PMID 31551934, 2019). "Notably, the weakened response to glucose in blood may reduce the insulin level, thereby lead to hyperglycemia, which further demonstrate the close association between hyperglycemia and AF." (PMID 31632440, 2019). "Similarly, the absence of changes in fasting blood glucose concentrations and glucose tolerance despite increased hepatic steatosis in WD-fed PIF1 KO females was surprising given the strong, positive association between liver fat, hyperglycemia and hepatic insulin resistance." (PMID 31136580, 2019). "This increased insulin requirement coupled with fear among health-care professionals of hypoglycaemia and associated adverse outcomes—especially overnight—might contribute to the prevalent hyperglycaemia in the control group." (PMID 30935872, 2019). "Currently, there is a paradigm shift in the classification of DM from the definition based on need of insulin therapy to achieve euglycaemia and age of disease onset or diagnosis to a definition based on an in-depth definition of the underlying aetiopathogenetic mechanisms of hyperglycaemia." (PMID 30783538, 2019). "The hyperglycaemia in leptin-deficiency impairs the host system to clear the bacteria from liver but leptin therapy may corrected the blood glucose levels by increasing insulin sensitivity and improved host resistance to this bacterial infection." (PMID 29868503, 2018). "T1DM is most often diagnosedamongst children and young people, and the production of endogenous insulin inpatients is significantly down by the time of the diagnosis; therefore, regularinsulin injections and continuous monitoring of blood glucose are necessary toreduce the risk of hyperglycemia." (PMID 29713516, 2018). "Insulin should be used to correct the hyperglycaemia caused by the administration of IV glucose and to reverse catabolism; it is important to monitor serum/plasma phosphate, magnesium, calcium and potassium during administration of IV insulin and to promptly correct electrolytic imbalance." (PMID 30522498, 2018). "Therefore, low-calorie PN, perhaps in conjunction with careful and appropriately monitored insulin administration, may reduce or prevent the occurrence of hyperglycemia and be effective in reducing hyperglycemia-associated cardiac complications." (PMID 29419661, 2018). "However, compared with hyperglycemia, the higher level of insulin is still deficient." (PMID 30356368, 2018). "In general, the regimens including Dex caused severe hyperglycemia which required insulin therapy, and most of them, except regimen 3 in which CAM (400 mg/day for 3 weeks) was combined with Len and Dex, could not be efficiently repeated due to DM aggravation or inefficacy of the regimens." (PMID 29454372, 2018). "Furthermore, we hypothesized that insulin administration would be associated with a greater increase in c-peptide levels in response to hyperglycemia." (PMID 28497374, 2017). "Interestingly, insulin dysfunction and hyperglycaemia are both risk factors for sporadic AD." (PMID 28402338, 2017).
Hyperglycemia (continued). "Although the use of glycemic control in patients with SIH or DH has been inconclusive as to whether tight glycemic control reduced the morbidity and mortality, however, this unknown condition of insulin administration in patients with hyperglycemia may cause a bias in the outcome assessment." (PMID 29295584, 2017). "Thus, fructose intake over a long period might alter the insulin signaling pathways and cause hyperglycemia and hyperinsulinemia, as shown by other studies." (PMID 29191195, 2017). "Because the Korean study did not consider the potential confounding of HP infection which might be closely related to insulin use, the higher risk of gastric cancer among insulin users could be explained by a deteriorating hyperglycemia associated with HP infection." (PMID 27587088, 2016). "Its classic manifestation consists of the biochemical triad of hyperglycemia, increased ketones in bloodstream, and metabolic acidosis, and it might be caused by several factors, including reduced secretion and action of insulin, and raised levels of anti-insulin hormones." (PMID 27527163, 2016). "Better control of hyperglycemia after a prolonged duration of insulin use may explain the attenuation of the hazard ratios for insulin use for ≥3 (or ≥5) years for all-cause mortality (mostly ascribed to diabetic vascular complications) and all-noncancer mortality." (PMID 26171401, 2015). "However, it remains unclear whether hyperglycemia contributes to the development of atherosclerosis in diabetes because many risk factors change with the impairment of insulin action." (PMID 26606676, 2015). "Since rapid-acting insulin given as a standard bolus will not last long enough to cover the long tail caused by protein and fat, altering the insulin delivery pattern (i.e., bolus type) may assist with controlling late postprandial hyperglycaemia in patients using IPT." (PMID 26202844, 2015). "However, triphenyltin exposure has been shown to cause hyperglycemia in rabbits and hamsters, possibly due to inhibitory effects on insulin secretion by decreasing the glucose-induced rise in intracellular Ca2+ in pancreatic beta-cells, as shown in triphenyltin exposed hamsters." (PMID 25883945, 2015). "Moreover, we wanted to examine whether the hyperglycemia type is associated with insulin dose and weight change after insulin initiation." (PMID 23880900, 2014). "Under this hypothesis, maternal hyperglycaemia is associated with increased placental transfer of glucose, resulting in fetal hyperglycaemia and increased insulin production, with the resultant effect being an increase in insulin-mediated fetal growth." (PMID 25315237, 2014). "The interferon cytokines, along with their risks of hyperglycemia and hyperlipidemia, may also cause apoptosis of pancreatic β cells and eventual pancreatic endocrine failure, and the T2D patient would need to start insulin therapy." (PMID 25334061, 2014). "The increase of insulin synthesis which itself is a potent antithrombotic humoral factor, has been reported to result in better prognostic outcome due to the control of hyperglycemia which is reported to be associated with the increase in the infarct size in AMI." (PMID 24558405, 2014). "Additionally, given that a reduced RHI has been associated with hyperglycaemia, it is useful to investigate whether daily variations in glucose and insulin influence PAT reliability." (PMID 24659234, 2014). "This would suggest that the mechanism of hyperglycemia in critically ill children with severe hyperglycemia is probably multifactorial and involve both a relative reduction in insulin production due to beta cell dysfunction whose cause of the is not well known, and peripheral resistance to insulin." (PMID 24628829, 2014). "Moreover, it could not be determined what was the driving force behind this association, i.e. insulin resistance or hyperglycemia resulting from β-cell dysfunction." (PMID 24595410, 2014).
Hyperglycemia (continued). "Identifying genetic markers which influence the progressive loss of beta cell function and hence the increasing need for insulin treatment may increase our understanding and knowledge underlying the progressive and uncontrolled hyperglycemia despite medical intervention." (PMID 25157406, 2014). "The symptoms were persistent hyperglycemia with weight loss, ketosis, and hyperlipidemia as well as specific β-cell destruction associated with signs of autoimmunity (increased levels of autoantibodies to glutamic acid decarboxylase-65, autoantigen IA-2 (islet cell antigen 512), and insulin)." (PMID 25574400, 2014). "However, specific associations between hyperglycemia, insulin, IGF-1, IGFBP3 and the risk of cancer among people with type 2 diabetes remain unclear." (PMID 23405181, 2013). "Insulin stimulates muscle and fat cells to remove glucose from the blood and stimulates the liver to metabolize glucose, causing the blood sugar level to decreases to the normal levels, as glucose is not metabolized; high amount of glucose is circulating in the blood (hyperglycemia)." (PMID 24151502, 2013). "Therefore, the diabetic milieu may represent a vicious cycle of hyperglycemia, nephrin loss, podocyte insulin resistance, exacerbated hyperglycemia resulting in a severe DN phenotype." (PMID 22615747, 2012). "Thus, MMS and TMS produced better insulin secretion patterns during hyperglycemia, which may be associated with elevated β-cell mass though increased hyperplasia." (PMID 22550941, 2012). "Furthermore, repetitive fluctuations in PG or insulin reportedly enhance monocyte adhesion to the endothelium of the rat thoracic aorta, and stable hyperglycemia or hyperinsulinemia has been found to cause less monocyte adhesion than does repetitive PG fluctuation." (PMID 22891922, 2012). "In contrast, hyperglycaemia causing mutations are located throughout the protein and most of them show a lower activity index, due to a reduction in substrate affinity combined or not with decreased catalytic turnover, which leads to an increased threshold for glucose-stimulated insulin release." (PMID 22291974, 2012). "We defined hospital acquired hyperglycaemia as glucose > 7.7 mmol/l (140 mg/dL), which is the cut-off value in the Recommendations of the American Heart Association and the trigger for initiation of insulin treatment for ICU patients recommended by the American College of Endocrinology." (PMID 20615210, 2010). "However, evidence shows that introducing insulin early in the adult population makes long-term glycemic control easier, which may perhaps revert damage caused by hyperglycemia to β cells and insulin sensitivity." (PMID 20718958, 2010). "However, chronic hyperglycemia is a cause of impairment of insulin biosynthesis and secretion." (PMID 20182627, 2010). "Although intensive insulin therapy lowers chronic hyperglycaemia and improves cardiovascular outcomes, it also increases the frequency of hypoglycaemic episodes, an emerging but poorly understood contributor to CVD risk." (PMID 41212210, 2026). "Injection pain and difficulties adjusting insulin during illness or hyperglycemia were frequent challenges, consistent with Indian research." (PMID 41529039, 2026). "The principal challenge is calculating the prandial insulin bolus to avoid hypoglycemia and hyperglycemia." (PMID 42187921, 2026). "Both developed hyperglycemia within the first days of life requiring short-term insulin therapy, followed by spontaneous normalization of glycemia." (PMID 41986760, 2026). "While the clinical definition involves persistent hyperglycaemia due to insulin irregularities, the daily reality of the disease is deeply rooted in the domestic sphere." (PMID 42074382, 2026). "STZ administration followed by partial insulin replacement, successfully induced moderate hyperglycaemia in mice." (PMID 41212210, 2026).